SLC1A5 (solute carrier family 1 member 5)
Diseases named in the same sentence as SLC1A5 in open-access papers (continued):
Sharing a sentence is not in itself a finding about the gene and the disease.
breast tumours (4 papers, 2018 to 2025). "Compared to that in invasive breast tumour cells, SLC1A5 protein expression in normal breast epithelium was lower." (PMID 39843491, 2025). "We therefore investigated SLC1A5 mRNA and SLC1A5 protein expression in a large number of breast tumours to better understand the potential role of this important transporter of Gln in BC and its molecular subtypes, particularly in luminal ER + disease." (PMID 39843491, 2025). "Apart from SLC7A8, all the following amino acid transporters, SLC7A5, SLC3A2, SLC7A11 and SLC38A2, were significantly expressed in breast tumours with high SLC1A5 expression (P < 0.01)." (PMID 39843491, 2025). "SLC1A5 protein was significantly expressed in breast tumours with high Ki67 (P < 0.001) and MYC (P = 0.02) expression." (PMID 39843491, 2025). "PIK3CA was also significantly expressed in breast tumours with high SLC1A5 expression (P = 0.005)." (PMID 39843491, 2025). "SLC1A5, GLS, PYCR1 and PIK3CA were significantly expressed in breast tumours with high expression of SLC7A5 (p < 0.001), while the low expression of SLC7A5 was associated with high levels of p-mTORC1 (p < 0.001)." (PMID 29566741, 2018). "SLC7A5, SLC1A5, GLS and PIK3CA were significantly expressed in breast tumours with high expression of SLC3A2 (p < 0.001), while the low expression was associated with high levels of p-mTORC1 (p < 0.001)." (PMID 29545595, 2018). "There was variable expression of the SLC1A5 protein in the membrane of breast tumour cells, ranging from absent to high." (PMID 39843491, 2025).
colorectal tumor (4 papers, 2015 to 2023). "Eventually, our in vitro findings are reinforced by the analysis of the TCGA gene expression datasets, showing that selected AATs (SLC1A5/ASCT2, SLC7A5/LAT1, and SLC38A2/SNAT2) are significantly upregulated in primary colorectal tumor tissues, compared with normal tissues." (PMID 34003553, 2021).
pancreatic adenocarcinoma (4 papers, 2022 to 2025). "Meanwhile, in pancreatic adenocarcinoma, high SLC1A5 expression can reduce the infiltrating levels of CD8+ T cells, and is negatively correlated with the immune enrichment of CD8+ T cells, cytotoxic cells, NK cells and CD4+ T cells." (PMID 36902506, 2023). "The high SLC1A5 expression in tumor cells may modulate tumor-infiltrating immune cells, as the knockdown of SLC1A5 expression recruits M2 macrophage infiltration to increase immunotherapy efficiency in pancreatic adenocarcinoma." (PMID 39223142, 2024). "Thus, SLC1A5 plays an inhibitory effect on the antitumor immune process in pancreatic adenocarcinoma." (PMID 36902506, 2023). "However, the roles of SLC1A5 in pancreatic adenocarcinoma (PAAD) remain elusive." (PMID 35419359, 2022).
pancreatic ductal adenocarcinoma (4 papers, 2017 to 2024). An infiltrating adenocarcinoma that arises from the epithelial cells of the pancreas. "Especially in the GSE43795 dataset, SLC1A5 was upregulated in two subtypes of PC, namely, solid-pseudopapillary neoplasm of pancreas (SPN) and pancreatic ductal adenocarcinoma (PCA), but was downregulated in the neuroendocrine tumor (NET)." (PMID 35419359, 2022).
small cell lung carcinoma (4 papers, 2017 to 2024). Small cell lung cancer (SCLC) is a highly aggressive malignant neoplasm, accounting for 10-15% of lung cancer cases, characterized byrapid growth, and early metastasis. "Circ-LDLRAD3 was an oncogenic factor in non-small cell lung cancer through miR-491-5P / mitogen-activated protein kinase kinase kinase 3 (MAP3K3) and miR-137 / lysine (K)-specific demethylase 1A (SLC1A5) pathways." (PMID 37587156, 2023).
stomach adenocarcinoma (4 papers, 2022 to 2023). "Similarly, SLC1A5 expression is associated with tumor-infiltrating immune cells in the TME of stomach adenocarcinoma." (PMID 36902506, 2023). "Moreover, recent studies demonstrated that SLC1A5 expression was positively and significantly associated with the abundance of tumor-infiltrating immune cells in stomach adenocarcinoma (STAD) and HCC." (PMID 35847985, 2022). "SLC1A5 is a novel prognostic biomarker that correlates with immune infiltrates in stomach adenocarcinoma via ferroptosis." (PMID 36275721, 2022).
Autoimmunity (3 papers, 2015 to 2021). The occurrence of an immune reaction against the organism's own cells or tissues. "Also, the Slc1a5 gene was downregulated in Itk–/– ncTregs, and previous work has shown that Slc1a5–/– mice are resistant to induction of T cell‐dependent autoimmunity." (PMID 34919342, 2021). "Furthermore, SLC1A5 played a role in experimental allergic encephalomyelitis (EAE), a murine model of T cell-mediated autoimmunity." (PMID 28553292, 2017).
Hyperglycemia (3 papers, 2022 to 2024). An increased concentration of glucose in the blood. "A prominent example is the reduction in SLC1A5 in MIC26 KO when compared with WT in hyperglycemia and normoglycemia." (PMID 39393820, 2024). "We further observed downregulation of many other amino acid transporters such as Slc1a5 and Slc7a5 by long-term hyperglycemia." (PMID 38742438, 2024). "Transcriptomics data revealed a reduction in SLC1A5 in MIC26 KOs, whereas proteomics revealed a significant reduction in normoglycemia and non-significant reduction in hyperglycemia in MIC26 KOs compared with WT." (PMID 39393820, 2024).
Insulin resistance (3 papers, 2016 to 2022). Increased resistance towards insulin, that is, diminished effectiveness of insulin in reducing blood glucose levels. "Concerning mRNAs, Slc1a5 was associated with hepatic glutamine uptake; Plp2 was able to increase ER-stress induced neuronal apoptosis while Cpeb1 was related with angiogenesis in chronic liver disease and involved in induction of insulin resistance." (PMID 27677588, 2016).
oral cancer (3 papers, 2017 to 2024). "This study concludes that the NEAT1/miR-125b-5p/SLC1A5 cascade modulates diverse activities in oncogenicity, treatment efficacy, and immune cell profiles in head and neck/oral carcinoma." (PMID 39223142, 2024).
periodontitis (3 papers, 2022 to 2024). An acute or chronic inflammatory process that affects the tissues that surround and support the teeth. "The ANN diagnostic model comprising four key genes—SLC1A5, SLC2A14, LURAP1L, and HERPUD1—demonstrated a high predictive efficacy for periodontitis with an AUC of 0.928 in the dataset." (PMID 38802844, 2024). "The ferroptosis-related genes identified in this study, including SLC1A5, SLC2A14, LURAP1L, and HERPUD1, may serve as novel diagnostic and therapeutic targets for periodontitis." (PMID 38802844, 2024). "Subsequently, through protein–protein interaction networks and multi-dataset machine learning algorithms, we further narrowed down these candidates to four key ferroptosis-related genes differentially expressed in periodontitis, namely SLC1A5, SLC2A14, LURAP1L, and HERPUD1." (PMID 38802844, 2024). "The ferroptosis-related genes SLC1A5, SLC2A14, LURAP1L, and HERPUD1 may serve as novel biomarkers for the diagnosis of periodontitis." (PMID 38802844, 2024). "Based on this, our study hypothesizes that ferroptosis-related genes, including SLC1A5, SLC2A14, LURAP1L, and HERPUD1, could be novel biomarkers for periodontitis." (PMID 38802844, 2024). "Moreover, the expression of ferroptosis-related genes, including NCOA4, SLC1A5, HSPB1, etc. were significantly upregulated in the human periodontitis-gingival samples compared to the periodontal healthy normal gingival samples." (PMID 37710216, 2023). "The expression levels of NCOA4, SLC1A5 and HSPB1 using PCR were significantly different between normal gingival samples and periodontitis samples." (PMID 35901060, 2022).
type 1 diabetes (3 papers, 2018 to 2022). "For six genes (ORMDL3, GALC, SPHK2, SLC1A5, PPARD and B4GALT1) the SNPs with the strongest association with type 1 diabetes (lowest p value) also acted as cis-eQTLs, suggesting that these SNPs regulate the expression of their associated genes." (PMID 29671030, 2018). "Next, we discovered eight gene polymorphisms (ORMDL3, SPHK2, B4GALNT1, SLC1A5, GALC, PPARD, PPARG and B4GALT1) involved in sphingolipid metabolism that contribute to the genetic predisposition to type 1 diabetes." (PMID 29671030, 2018).
chondrosarcoma (2 papers, 2023 to 2024). A malignant cartilaginous matrix-producing mesenchymal neoplasm arising from the bone and soft tissue. "The pharmacological inhibition of SLC1A5 or GLS was shown to antagonize cisplatin-induced cell death in parental chondrosarcoma and SW1353-R-AR shRNA cells." (PMID 37928274, 2023). "In the current study, we observed elevated SLC1A5 expression levels in cisplatin-resistant chondrosarcoma cells." (PMID 37928274, 2023). "The knockdown of AR expression in cisplatin-resistant chondrosarcoma cells was shown to reduce the expression of SLC1A5 and GLS in vivo." (PMID 37928274, 2023). "This means that the MEK and ERK signaling pathways regulate SLC1A5 and GLS expression as well as glutamine metabolism in cisplatin-resistant chondrosarcoma." (PMID 37928274, 2023). "The further development of AR, SLC1A5 and GLS inhibitor or antibodies are potential candidates to treat of cisplatin-resistant chondrosarcoma." (PMID 37928274, 2023). "The MEK, ERK, and NrF2 signaling pathways were shown to regulate AR-mediated alanine-serine-cysteine transporter 2 (ASCT2; also called SLC1A5) and glutaminase (GLS) expression as well as glutamine metabolism in cisplatin-resistant chondrosarcoma." (PMID 37928274, 2023). "The MEK, ERK, and NrF2 signaling pathways were shown to control AR-mediated SLC1A5 and GLS expression as well as glutamine metabolism in cisplatin-resistant chondrosarcoma." (PMID 37928274, 2023). "In cisplatin-resistant chondrosarcoma, the MEK, ERK, and NrF2 signaling pathways regulate AR-mediated SLC1A5 and GLS expression as well as glutamine metabolism." (PMID 37928274, 2023). "However, we don't have tissue samples from clinic individuals, the impact of AR, SLC1A5 and GLS on cisplatin-resistant chondrosarcoma needs to be assessed in patients." (PMID 37928274, 2023).
colon adenocarcinoma (2 papers, 2018 to 2021). "Transfected SW480 cells (cell line from colon adenocarcinoma) with PPARβ/δ transgenes showed high mRNA and protein levels of GLUT1 and SLC1-A5 (solute carrier family 1 member 5), and as a consequence, lactate increases, and there is also high glucose and glutamine consumption." (PMID 29966227, 2018).
head and neck cancer (2 papers, 2024 to 2025). A primary or metastatic malignant neoplasm affecting the head and neck. "Among them, 6 genes were highly expressed in head and neck cancers, namely SLC1A5, ETS1, NDRG1, RHEB, HIF1A and CDH2." (PMID 41317550, 2025).
liver inflammation (2 papers, 2023 to 2024). "Furthermore, the HMBOX1/SLC1A5-mediated reduction in glutamine uptake may represent a potential mechanism underlying the protective effects of HMBOX1 in liver inflammation." (PMID 39698464, 2024). "Therefore, HMBOX1/SLC1A5-mediated downregulation of glutamine uptake may be one mechanism for the protective effects of HMBOX1 in liver inflammation." (PMID 37208615, 2023).
ovarian tumor (2 papers, 2017 to 2024). "Autophagy regulation via claudin-4/SLC1A5/LAT1 has the potential to be a targetable mechanism to interfere with genomic instability in ovarian tumor cells." (PMID 38867360, 2024). "Together, the inhibition of autophagy or its activation led to changes in the intracellular distribution of SLC1A5, supporting its involvement in the regulation of autophagy in ovarian tumor cells." (PMID 38867360, 2024). "Protein expression of apoptosis and angiogenesis regulators versus SLC1A5 status in ovarian tumors (n = 121)." (PMID 28609484, 2017). "Also, SLC1A5 and LAT1 inhibition resulted in autophagy upregulation in different ovarian tumor cells, suggesting an association of claudin-4 with these amino acid transporters as a potential element regulating autophagy." (PMID 38867360, 2024).
papillary thyroid cancer (2 papers, 2019 to 2022). "SLC1A5 is a target of miR-199a-5p, and ABHD11-AS1 promotes papillary thyroid cancer progression by regulating SLC1A5 expression via sponging miR-199a-5p." (PMID 36499136, 2022). "In papillary thyroid cancer tissues and cell lines, ABHD11-AS1 and SLC1A5 expression levels were found to be increased." (PMID 36499136, 2022).
renal cell carcinoma (2 papers, 2023 to 2025). "Meanwhile, high SLC1A5 expression abolished the inhibitory effect of miR-125a-5p in renal cell carcinoma." (PMID 41317550, 2025).
schizophrenia (2 papers, 2008 to 2022). A major psychotic disorder characterized by abnormalities in the perception or expression of reality. "Alterations in solute carrier family genes, such as SLC2A6, SLC1A5, and SLC22A4, have been implicated in the impairment of the synaptic transmission, which seems relevant to the pathology of schizophrenia." (PMID 35012632, 2022). "We investigated the association of SLC1A4, SLC1A5, SLC6A5 and SLC6A9 genes with schizophrenia in the Japanese population by analysing total 21 common SNPs." (PMID 18638388, 2008). "In this study we report association studies of schizophrenia with total 21 SNPs distributed in genes SLC1A4, SLC1A5, SLC6A5 and SLC6A9 that encoding the neutral amino acid transporters ASCT1, ASCT2 and the glycine transporters GLYT2, GLYT1, respectively." (PMID 18638388, 2008). "We report here association studies of schizophrenia with SLC1A4, SLC1A5 encoding neutral amino acid transporters ASCT1, ASCT2, and SLC6A5, SLC6A9 encoding glycine transporters GLYT2, GLYT1, respectively." (PMID 18638388, 2008). "Moreover, exclusion of linkage between schizophrenia and SLC1A5 in 23 English and Icelandic schizophrenia families was reported." (PMID 18638388, 2008). "There has been no linkage with schizophrenia reported to the chromosome regions where SLC1A5, SLC6A5 or SLC6A9 are located." (PMID 18638388, 2008). "We conclude that at least one susceptibility locus for schizophrenia is located within or nearby SLC6A5, whereas SLC1A4 SLC1A5 and SLC6A9 are unlikely to be major susceptibility genes for schizophrenia in the Japanese population." (PMID 18638388, 2008). "We concluded that at least one susceptibility locus for schizophrenia may be located within or nearby SLC6A5, whereas SLC1A4, SLC1A5 and SLC6A9 are unlikely to be major susceptibility genes for schizophrenia in the Japanese population." (PMID 18638388, 2008).
skin cancer (2 papers, 2021). "Prognostic analysis of data from PrognoScan and Kaplan-Meier plotter showed that high SLC1A5 expression correlated with a poor prognosis in bladder, brain, breast, gastric, and skin cancers." (PMID 34367941, 2021).
squamous cell carcinoma (2 papers, 2019 to 2025). A carcinoma arising from squamous epithelial cells. "Adenocarcinomas showed higher expression of SLC1A5 and GLS2 in both protein (P = 0.08 and P = 0.019, respectively) and mRNA level (P < 0.001 and P = 0.003, respectively), compared to squamous cell carcinomas." (PMID 31668020, 2019).
type 2 diabetes (2 papers, 2018 to 2021). "In this study, we replicated five CpGs in blood, from which four reside in the genes previously shown to be associated with type 2 diabetes (ABCG1, LOXL2, SLC1A5, SREBF1)." (PMID 29164275, 2018). "In our Lifelines sample, five out of 52 included CpGs showed significant associations with type 2 diabetes (the Bonferroni-adjusted p < 0.0009 (0.05/52 CpGs)), including the loci in the ABCG1, LOXL2, TXNIP, SLC1A5 and SREBF1 genes (see a short description in ESM Box 1)." (PMID 29164275, 2018).
adrenocortical carcinoma (1 paper, 2025). "In adrenocortical carcinoma (ACC) cells, curcumin compels tumor cells to depend on glutamine metabolism for compensatory adaptation by upregulating the expression of SLC1A5 and GLS1." (PMID 41515171, 2025).
alcoholic liver diseases (1 paper, 2024). A disorder caused by damage to the liver parenchyma due to alcohol consumption. "There were similar results in single-gene GSEA analysis of SLC1A5, and both SLC1A5 and SLC7A5 were closely related to alcoholic liver disease, which is known as a common genesis of liver fibrosis around the world." (PMID 39698464, 2024).
diabetic kidney disease (1 paper, 2026). Progressive kidney disorder caused by vascular damage to the glomerular capillaries, in patients with diabetes mellitus. "In diabetic kidney disease, a hyperglycemic environment upregulates SLC1A5 expression via KPNA2, activating the mTORC1/p70S6K pathway to inhibit autophagy." (PMID 41601931, 2026).
epilepsies (1 paper, 2020). "Taken together, our data and previous reports raise the possibility that central glutamine deficiency may upregulate slc1a5 and Slc7a5 gene expression, activate the mTOR pathway, and contribute to astrogliosis and epilepsy, some of the key features of experimental SSADHD." (PMID 33204597, 2020).
Hypertension (1 paper, 2022). The presence of chronic increased pressure in the systemic arterial system. "Interestingly, differential methylation at multiple genes (SLC7A11, PHGDH, TXNIP, LOC100132354, CPT1A, SLC1A5) is associated with both AC (this study) and with hypertension." (PMID 34857913, 2022).
latent infection (1 paper, 2015). "Therefore, during latent infection of endothelial cells, KSHV activates and requires the Myc/MondoA-network to upregulate the glutamine transporter, SLC1A5, leading to increased glutamine uptake for glutaminolysis." (PMID 26197457, 2015).
liver fibrosis (1 paper, 2024). "Then we speculate that immune checkpoints might correlate with HSC activation and liver fibrosis and found that SLC1A5 was significantly negatively associated with CTLA4, LAG3, and PDCD1; similarly, SLC7A5 was significantly negatively associated with CTLA4 and LAG3." (PMID 39698464, 2024). "Taken together, we automatically hypothesized that upregulated SLC7A5 and SLC1A5 might contribute to the development of liver fibrosis by suppressing the expression of the immune checkpoint and inducing the anomalous immunocyte activation intrahepatic." (PMID 39698464, 2024).
lupus (1 paper, 2025). "Activated cTfh cells showed increased SLC1A5 and GLS expression (but not GLUD1) (orange group), indicating active glutamine metabolism, known to be critical for Th17 cells and disease severity in lupus mice." (PMID 40693461, 2025).
memory impairment (1 paper, 2022). "We also discovered that ATF3 was considerably overexpressed in the hippocampal CA1 area, and gene markers of ferroptosis, such as GPX4, SLC7A11, SLC1A5, and PTGS2, were dysregulated in the CCI-induced memory impairment paradigm." (PMID 35547819, 2022). "Similarly, lipid peroxidation and gene markers (GPX4, SLC7A11, SLC1A5, and PTGS2) dysregulation of ferroptosis were discovered in the CCI-induced memory impairment model." (PMID 35547819, 2022).
metastatic cancer (1 paper, 2024). A carcinoma which has spread from the original site of growth to another anatomic site. "Analysis of EVs of TKI-resistant cancer cells as well as plasma of patients with TKI-resistant metastatic cancer reveal an enrichment in SLC1A5 and SLC25A5 solute carrier transporters and ALDHA1." (PMID 39431017, 2024).
nephrotic syndrome (1 paper, 2025). A collection of symptoms that include severe edema, proteinuria, and hypoalbuminemia; it is indicative of renal dysfunction. "Further classification into nephrotic syndrome (NS) (urinary protein > 3.5 g/day + serum albumin <30 g/L) and non-NS groups revealed elevated SLC1A5 expression in the NS group (p = 0.047)." (PMID 41189572, 2025).